IFNAR2 (interferon alpha and beta receptor subunit 2)
Description:
Together with IFNAR1, forms the heterodimeric receptor for type I interferons (including interferons alpha, beta, epsilon, omega and kappa). Type I interferon binding activates the JAK-STAT signaling cascade, resulting in transcriptional activation or repression of interferon-regulated genes that encode the effectors of the interferon response. Mechanistically, type I interferon-binding brings the IFNAR1 and IFNAR2 subunits into close proximity with one another, driving their associated Janus kinases (JAKs) (TYK2 bound to IFNAR1 and JAK1 bound to IFNAR2) to cross-phosphorylate one another. The activated kinases phosphorylate specific tyrosine residues on the intracellular domains of IFNAR1 and IFNAR2, forming docking sites for the STAT transcription factors (STAT1, STAT2 and STAT). STAT proteins are then phosphorylated by the JAKs, promoting their translocation into the nucleus to regulate expression of interferon-regulated genes. [Isoform 3]: Potent inhibitor of type I IFN receptor activity.
Synonyms: IFN-R-2; IFNABR; IFNARB; IFN-R; IFN-alpha-REC; IMD45
Tractability: Small molecule: it has a binding pocket of medium quality. Antibody: UniProt places it where antibodies can reach, with high confidence; its Gene Ontology location is reachable by antibodies, with high confidence; UniProt predicts a signal peptide or a membrane-spanning region. PROTAC: ubiquitination databases record sites on it. Other modalities: an approved drug acts on it.
Gene: Protein-coding gene on chromosome 21 (33,205,282 to 33,265,675, forward strand). Ensembl gene ENSG00000159110.
Subcellular location: Cell membrane (Isoform 1); Cell membrane (Isoform 2); Secreted (Isoform 3)
Pathways (Reactome):
Disease: Evasion by RSV of host interferon responses; Potential therapeutics for SARS; SARS-CoV-2 activates/modulates innate and adaptive immune responses
Immune System: Interferon alpha/beta signaling; Regulation of IFNA/IFNB signaling
Gene Ontology:
Molecular function: cytokine binding; protein binding; protein kinase binding; type I interferon receptor activity; JAK pathway signal transduction adaptor activity
Biological process: cell surface receptor signaling pathway via JAK-STAT; cellular response to interferon-beta; defense response to virus; response to interferon-alpha; response to interferon-beta; type I interferon-mediated signaling pathway; cell surface receptor signaling pathway; cellular response to virus; response to virus; regulation of receptor signaling pathway via JAK-STAT
Cellular component: extracellular region; plasma membrane; receptor complex; membrane
Genetic constraint (gnomAD): Loss-of-function variants: 16 observed, 31.94 expected, observed/expected ratio (o/e) 0.5, 90% interval 0.34 to 0.76. The upper end of that interval is the gene's LOEUF score, 0.76, which puts it in group 3 of 6, group 1 being the genes least tolerant of losing a copy. Missense variants: 456 observed, 491.69 expected, observed/expected ratio (o/e) 0.93, 90% interval 0.86 to 1. Synonymous variants: 179 observed, 188.02 expected, observed/expected ratio (o/e) 0.95, 90% interval 0.84 to 1.08.
Homologues: Orthologues: chimpanzee IFNAR2 (96% identical), macaque IFNAR2 (88% identical), dog IFNAR2 (57% identical), pig IFNAR2 (56% identical), rabbit IFNAR2 (54% identical), rat Ifnar2 (47% identical), mouse Ifnar2 (46% identical), zebrafish il10ra (12% identical), zebrafish ifnlr1 (11% identical), zebrafish crfb15 (9% identical), zebrafish ifngr2 (9% identical), zebrafish ifngr1l (8% identical), and 3 more. Paralogues in human: IL20RA (14% identical), IFNLR1 (13% identical), IFNGR1 (12% identical), IL10RA (12% identical), IL22RA1 (11% identical), F3 (11% identical), IFNAR1 (10% identical), IFNGR2 (10% identical), IL10RB (9% identical), IL22RA2 (9% identical), IL20RB (8% identical).
Diseases named in the same sentence as IFNAR2 in open-access papers:
IFNAR2 is named in the same sentence as 146 diseases in open-access papers, as found by Europe PMC text mining. Sharing a sentence is not in itself a finding about the gene and the disease. The quoted sentences say what the papers report.
COVID-19 (110 papers, 2020 to 2026). A disease caused by infection with severe acute respiratory syndrome coronavirus 2. "Next, to validate the association of IFNAR2 p.F8S with severe COVID-19 phenotypes, such as hospitalization due to COVID-19, we interrogated the publicly available HGI meta-analysis results (n = 26,167 cases and n = 2061,934 controls)." (PMID 41596638, 2026). "This scenario was also supported by the results of the conditional analysis, showing that p.F8S has the largest effect size on the risk of severe COVID-19 among IFNAR2 variants in the global HGI cohort." (PMID 41596638, 2026). "In this study, we first identified the low-frequency p.F8S missense variant at the IFNAR2 gene locus as an independent genetic marker associated with COVID-19 severity." (PMID 41596638, 2026). "In keeping with results obtained during COVID-19, the p.F8S variant was associated with lower IFNAR2 mRNA levels, both at baseline and following IFN-α exposure (β = −0.502, p = 0.010)." (PMID 41596638, 2026). "Remarkably, the IFNAR2 locus independently emerged from previous genome-wide association studies (GWAS) as one of the main genetic determinants of COVID-19 severity." (PMID 41596638, 2026). "In conclusion, the IFNAR2 p.F8S missense variant is associated with predisposition to severe COVID-19 and an altered response to SARS-CoV-2 infection at the transcriptional level in immune cell populations." (PMID 41596638, 2026). "In the same experiment, we also compared the effect on the same outcomes of the IFNAR2 rs13050728 intronic variant linked with protection against COVID-19 (wild-type, n = 6; heterozygous, n = 3; homozygous, n = 3)." (PMID 41596638, 2026). "By analyzing local and global cohorts, we showed that an additional, low frequency IFNAR2 variant, namely p.F8S, associates with an increased risk of severe COVID-19 requiring hospitalization." (PMID 41596638, 2026). "In particular, the non-coding rs2236757 variant at the IFNAR2 locus was associated with severe COVID-19, while the intronic rs13050728 with protection against critical illness and hospitalization." (PMID 41596638, 2026). "In this work, the authors established that an IFNAR2-rs13050728 risk variation associated with COVID-19 showed context- and monocyte-specific expression quantitative trait loci effects." (PMID 39714149, 2025). "Rare loss-of-function mutations in IFNAR2 are associated with severe COVID-19 and many other viral infections." (PMID 40429912, 2025). "The strong effect of LZTFL1 on COVID-19 susceptibility is in accordance with the data in the literature, while the effect of the IFNAR2 minor variant has been variably observed." (PMID 39752416, 2025). "IFNAR2 has been implicated in disease severity, with Mendelian randomization studies suggesting a potential causal relationship between genetic variations in IFNAR2 and COVID-19 severity." (PMID 40543387, 2025). "Polymorphisms in IFNAR2, such as rs2236757, rs2834158, rs3153, and rs1051393, have also been linked to an increased risk of COVID-19 mortality." (PMID 40543387, 2025). "One particular study has indicated that a common genetic variant within the IFNAR2 gene (rs2236757) is strongly associated with COVID-19 severity." (PMID 39435115, 2024). "Recent studies have reported the association of the IFNAR2 gene with the most severe forms of COVID-19, as well as the relationship of generic variants with more critical cases of the disease." (PMID 38543725, 2024). "A study conducted in a Mexican cohort investigated IFNAR2 variants (rs2236757, rs1051393, rs3153, rs2834158, and rs2229207) using Taqman® assays in 1,202 patients with severe COVID-19." (PMID 39351231, 2024). "A higher expression of IFNAR2 was linked to a reduced probability of critical COVID-19, and TYK2 expression had a role in regulating IFNAR signaling." (PMID 38741892, 2024). "Specifically, the study identified a link between an SNP within the human IFNAR2 gene (rs2236757 polymorphism) and COVID-19 severity." (PMID 39435115, 2024).
COVID-19 (continued). "In essence, evidence is accumulating linking the IFNAR2 gene with the severity, mortality and susceptibility to COVID-19, indicating a crucial role of this gene in determining the course of this disease." (PMID 39435115, 2024). "Several lines of investigation, including genome-wide association studies (GWASs), transcriptomic analyses, and single-cell studies, have focused on IFNAR2 (rs2236757) as a potential genetic risk factor for severe COVID-19." (PMID 39296547, 2024). "Associations between the IFNAR2 locus and COVID-19 severity have been identified through various GWAS and multi-omic analyses." (PMID 38741892, 2024). "According to recent research, severe instances of COVID-19 were associated with decreased expression of IFNAR2 at 21q22.1 and increased expression of a gene near TYK2 at 19p13.2." (PMID 38741892, 2024). "Individuals with certain IFNAR2 polymorphisms have a higher risk of severe COVID-19 and increased mortality due to impaired antiviral response." (PMID 39351231, 2024). "Recent genome-wide association studies (GWAS), involving 2244 patients with COVID-19, have revealed an association between single nucleotide polymorphism (SNP) within the interferon α/β receptor 2 (IFNAR2) gene and COVID-19 severity." (PMID 39435115, 2024). "Supporting evidence has emerged from studies focused on genes associated with COVID-19 severity, where a specific variant within the IFNAR2 gene (rs2236757) has been linked to poorer clinical outcomes." (PMID 39296547, 2024). "Using GWAS, IFNAR2 variants were related to susceptibility, COVID-19 severity, or poor disease outcome." (PMID 38003785, 2023). "All these pieces of evidence support the consideration of the monoallelic or biallelic IFNAR2-Ser8 variant as a robust risk marker of severe COVID-19." (PMID 37760989, 2023). "GWAS in the European population with severe COVID-19 showed that the C allele of rs2834161 (IFNAR2) was associated with respiratory failure (p = 6.1 × 10−7, OR = 1.25)." (PMID 38003785, 2023). "The study of genetic mechanisms critical to COVID-19 also underlined that the low expression of IFNAR2 is associated with life-threatening disease, while its high expression reduces the odds of severe COVID-19." (PMID 37896870, 2023). "To do this, we pose the following research question: do the risk variants in SNVs of IFNAR1 or IFNAR2 of patients with severe COVID-19 affect the antiviral immune response or lead to poor outcomes compared to noncarriers individuals of risk variants?" (PMID 38003785, 2023). "Our data presented the dysfunction of monocytes or DC, particularly ncMono, in severe COVID-19, the enrichment of host genetics COVID-19 risks in monocytes or DC, as well as COVID-19 context-specific eQTL effect of the IFNAR2 variant (rs13050728) in monocytes." (PMID 37095364, 2023). "GWAS of 52,630 patients of four cohorts with COVID-19 replicated the association with disease severity and rs2236757 of IFNAR2." (PMID 38003785, 2023). "This systematic review aimed to describe IFNAR1 and IFNAR2 variants associated with COVID-19 susceptibility and severity." (PMID 38003785, 2023). "Rare variants in IFNAR2 (rs72550721, A) produce a Tyr322Ter change that results in a stop codon, causing a loss of function in IFNAR2, which in the Asiatic population was associated with increased susceptibility to severe COVID-19." (PMID 38003785, 2023). "Among other interesting findings from this study were different rare variants (MAF < 1%) of IFNAR2 detected among hospitalized severe COVID-19-positive patients." (PMID 38003785, 2023). "Recently, the association of the common variant p.Phe8Ser (rs2229207) affecting interferon receptor gene IFNAR2 to severe COVID-19 has been proposed in several case-control studies." (PMID 37760989, 2023). "Regression analysis showed that COVID-19 susceptibility in children increases in cases of interactions of IFNAR2 rs2236757, OAS1 rs10774671, OAS3 rs10735079, CD40 rs4813003 and CASP3 rs113420705." (PMID 37896870, 2023).
COVID-19 (continued). "In conclusion, our study revealed that the IFNAR2 rs2236757A variant was associated with critical COVID-19 illness." (PMID 37745867, 2023). "On the other hand, Mendelian randomization showed significant results for the variant rs13050728 (IFNAR2), with the strongest correlation with COVID-19 hospitalization (OR = 1.17, p = 1.88 × 10−12)." (PMID 38003785, 2023). "This systematic review aimed to describe SNV in IFNAR1 and IFNAR2 genes associated with a high risk of viral infection or clinical relevance in COVID-19." (PMID 38003785, 2023). "The combined analysis of the presence of at least one of our two genetics biomarkers related to inflammasome activity (MEFV) and antiviral immunity (IFNAR2) was associated with an increase in COVID-19 severity risk with an OR of 6.274 (95% CI) (2.430–16.201)." (PMID 37760989, 2023). "IFNAR2 rs2236757 risk A allele was revealed significantly more often among patients with severe COVID-19 and MIS-C compared to the control group—56.67% vs. 33.33% (p = 0.046)." (PMID 37896870, 2023). "In the current study, we found that the risk allele IFNAR2 rs2236757A is significantly associated with critical COVID-19 illness." (PMID 37745867, 2023). "A COVID-19-associated risk variant at the IFNAR2 locus (rs13050728) had context-specific and monocyte-specific expression quantitative trait loci effects." (PMID 37095364, 2023). "Many rare loss-of-function variants in IFN-pathway genes such as TLR3, IRF3, IRF7, IFNAR1, and IFNAR2 were identified to be associated with severe COVID-19 through impairing IFN immunity." (PMID 36531218, 2022). "Using Mendelian randomization, the authors also found evidence that lower expression of IFNAR2 is associated with life-threating COVID-19." (PMID 36672770, 2022). "Two children from Canada and Alaska that respectively developed recurrent severe COVID-19 or fatal COVID-19 were shown to harbour the same homozygous mutation in IFNAR2 (p.(Ser53Pro))." (PMID 35986347, 2022). "GWAS studies have identified rs13050728 and its closest gene, IFNAR2, to be in the five most significant risk variants associated with critically ill COVID-19 patients (p = 1.045 × 10−16, app.covid19hg.org/variants, accessed June 202o)." (PMID 36672763, 2022). "A GWAS also reported that an intron variant rs2236757 in the IFNAR2 gene increased the odds of severe COVID-19." (PMID 36204639, 2022). "Reduced expression of IFNAR2 in immune cells has been shown to be associated with a higher risk of COVID-19, likely due to impaired interferon signaling in the blood." (PMID 35446421, 2022). "In particular, autosomal-recessive deficiencies in IRF7 and IFNAR1 and autosomal-dominant deficiencies in TLR3, TBK1, IRF3, IRF7, IFNAR1 and IFNAR2 genes have been found in a small percentage of patients with severe influenza and COVID-19." (PMID 35846766, 2022). "IFNAR1 (p.Trp73Cys, p.Ser422Arg, p.Pro335del) and IFNAR2 (p.Glu140fs) variants were identified in patients with life-threatening COVID-19, highlighting the importance of type I IFN production in severe disease." (PMID 36204639, 2022). "Association analysis of IFNAR2 haplotypes (rs3153/rs2229207/rs1051393/rs2834158) with mortality risk among patients with severe COVID-19." (PMID 35967349, 2022). "The association of IFNAR2 locus with COVID-19 severity has been reported in different GWAS and multi-omic analyses, as well as in a transcriptome-wide association study." (PMID 35967349, 2022). "First, the index SNP for COVID-19 susceptibility in 21q22.11, rs130507285, falls within an intronic region of IFNAR2 (less than 24kbp from IL10RB)." (PMID 36064543, 2022). "FOXP4-AS1 and IFNAR2 were also significantly associated in the integrated analysis of the Japanese GWAS and international meta-GWAS when compared with severe COVID-19 cases and the general population." (PMID 35264675, 2022).
COVID-19 (continued). "FOXP4-AS1 and IFNAR2 genes also showed genome-wide significant associations in the integrated analysis comparing severe COVID-19 patients and the general population." (PMID 35264675, 2022). "Our study confirms that IFNAR2 is important for COVID-19 susceptibility; however, we prioritized IL10RB over IFNAR2 as a suitable gene target for novel therapeutic development." (PMID 36064543, 2022). "Mutation in the IFNAR2 was reported to associate with critical illness in COVID-19 in a previous GWAS as well." (PMID 35360730, 2022). "While DPP9 and TYK2 are thought to be associated with host-driven inflammatory lung injury linked to life-threatening COVID-19, IFNAR2 and OAS genes have been associated with innate antiviral defences." (PMID 34575070, 2021). "Here, we found that colocalized severe COVID-19-risk variants in chromosome 21 were associated with reduced expression of the gene encoding interferon receptor 2 (IFNAR2) in 12 of the 13 immune cell types analyzed." (PMID 34799557, 2021). "Genome-wide association studies (GWAS) in severe COVID-19 also identified genes for the IFNAR2 subunit and OAS as required to protect against critical illness." (PMID 34360686, 2021). "We found that severe COVID-19-risk variants in the IFNAR2 locus (chromosome 21) were colocalized with eQTLs linked to increased expression of the neighboring gene IL10RB in NK cells and T-cell subsets (rs12482556, adj." (PMID 34799557, 2021). "Polymorphisms of IFNAR2 andTYK2 (involved in the initiation of type I IFN signaling)were also associated with critical COVID-19 in a recent GWAS of individuals ofmostly European descent (Pairo-Castineira etal., 2020)." (PMID 34436508, 2021). "TWAS also showed a significant association of COVID-19 severity with reduced expression of IFNAR2 in multiple immune cell types, thus supporting a role for impaired interferon signaling in immune cells in the pathogenesis of severe COVID-19 illness." (PMID 34799557, 2021). "IFNAR2 has been implicated in severe COVID-19, based on mendelian randomization, genome-wide associations, and gene expression changes." (PMID 34616619, 2021). "The C allele at rs13050728 associated with higher IFNAR2 expression in all tissues (except skeletal muscle), lower risk of COVID-19 hospitalization, and lower levels of plasma VEGFR2 and TPSG1." (PMID 33837377, 2021). "Other innate immune genes upstream of OAS1 that are associated with severe COVID-19 in a genome wide association study are IFNAR2, and TYK2, which are in the type I IFN pathway." (PMID 34342578, 2021). "We are the first to implicate a causal role for ACE2 in COVID-19 manifestations using MR techniques; we have also implicated IFNAR2 in COVID-19, concordant with recent studies." (PMID 33837377, 2021). "The p.F8S variant displayed a low linkage with the leading IFNAR2 gene variants associated with severe COVID-19 susceptibility in previous GWAS, and the association with severe disease outcomes persisted after extensive correction for multiple genetic and clinical risk factors." (PMID 41596638, 2026). "Taken together, these results suggest that IFNAR2 p.F8S may represent a genetic modifier contributing to the increased risk of severe COVID-19 linked with the IFNAR2 locus." (PMID 41596638, 2026). "Regarding the genetic polymorphisms, a higher allele frequency of the LZTFL1 and IFNAR2 minor variants significantly correlated with greater COVID-19 disease susceptibility (hospitalization) and severity, and a similar tendency was observed for the RAVER1 and the MUC5B variants." (PMID 39752416, 2025). "Furthermore, the GWAS signals for COVID-19 susceptibility and severity at the IFNAR2 locus (encoding the interferon α/β receptor 2) colocalized with a cis-eQTL, and cis-sQTLs associated with 10 splicing events in this gene." (PMID 40038547, 2025).